MAP4K1 (mitogen-activated protein kinase kinase kinase kinase 1)
Description:
Serine/threonine-protein kinase, which plays a role in the response to environmental stress. Appears to act upstream of the JUN N-terminal pathway. Activator of the Hippo signaling pathway which plays a pivotal role in organ size control and tumor suppression by restricting proliferation and promoting apoptosis. MAP4Ks act in parallel to and are partially redundant with STK3/MST2 and STK4/MST2 in the phosphorylation and activation of LATS1/2, and establish MAP4Ks as components of the expanded Hippo pathway. May play a role in hematopoietic lineage decisions and growth regulation. Together with CLNK, it enhances CD3-triggered activation of T-cells and subsequent IL2 production (By similarity).
Synonyms: HPK1
Tractability: Small molecule: a structure with a bound ligand is known; a high-quality ligand is known; it belongs to a druggable protein family. Antibody: the Human Protein Atlas places it where antibodies can reach. PROTAC: it is named in the literature on targeted protein degradation; UniProt records ubiquitination sites on it; ubiquitination databases record sites on it; its protein half-life has been measured; a small molecule that binds it is known.
Target class: Protein Kinase; STE protein kinase STE20 family; STE protein kinase group; Enzyme; Kinase; STE protein kinase KHS subfamily
Chemical probes: HPK1-IN-3, PF-07265028
Safety:
Unwanted effects reported when the protein is acted on. In parentheses: how it was acted on, where the effect was seen, and who reports it.
cardiac arrhythmia (cardiovascular system; source: Lamore et al. (2017))
Gene: Protein-coding gene on chromosome 19 (38,587,641 to 38,619,161, reverse strand). Ensembl gene ENSG00000104814.
Subcellular location (Human Protein Atlas): Plasma membrane
Gene Ontology:
Molecular function: ATP binding; MAP kinase kinase kinase kinase activity; protein binding; protein serine kinase activity; protein serine/threonine kinase activity; protein kinase activity
Biological process: cell population proliferation; cellular response to phorbol 13-acetate 12-myristate; JNK cascade; peptidyl-serine phosphorylation; positive regulation of MAPK cascade; protein autophosphorylation; protein phosphorylation; intracellular signal transduction
Cellular component: membrane; cytoplasm
Genetic constraint (gnomAD): Loss-of-function variants: 35 observed, 117.47 expected, observed/expected ratio (o/e) 0.3, 90% interval 0.23 to 0.4. The upper end of that interval is the gene's LOEUF score, 0.4, which puts it in group 1 of 6, group 1 being the genes least tolerant of losing a copy. Missense variants: 789 observed, 1,063.3 expected, observed/expected ratio (o/e) 0.74, 90% interval 0.7 to 0.79. Synonymous variants: 412 observed, 415.63 expected, observed/expected ratio (o/e) 0.99, 90% interval 0.91 to 1.08.
Homologues: Orthologues: macaque MAP4K1 (98% identical), chimpanzee MAP4K1 (94% identical), pig MAP4K1 (94% identical), guinea pig MAP4K1 (91% identical), rat Map4k1 (87% identical), mouse Map4k1 (86% identical), tropical clawed frog map4k5 (53% identical). Paralogues in human: MAP4K3 (48% identical), MAP4K5 (46% identical), MAP4K2 (43% identical), MAP4K4 (27% identical), MINK1 (26% identical), TNIK (26% identical), NRK (22% identical), STK10 (21% identical), SLK (21% identical), TAOK1 (21% identical), TAOK3 (20% identical), TAOK2 (19% identical), and 23 more.
Diseases named in the same sentence as MAP4K1 in open-access papers:
MAP4K1 is named in the same sentence as 50 diseases in open-access papers, as found by Europe PMC text mining. Sharing a sentence is not in itself a finding about the gene and the disease. The quoted sentences say what the papers report.
colon carcinoma (7 papers, 2007 to 2019). "PDCD4 inhibited colon cancer cell invasion through suppressing mitogen-activated protein kinase kinase kinase kinase 1 (MAP4K1), leading to suppressed AP-1 dependent transcription." (PMID 22272332, 2012). "A recent study showed that PDCD4 suppressed tumor progression in human colon carcinoma cells by the novel mechanism of down-regulating MAP4K1 transcription, with consequent inhibition of c-Jun activation and AP-1-dependent transcription." (PMID 18570662, 2008). "Interestingly PDCD4, suppresses tumor progression in human colon carcinoma cells by down-regulating the MEK kinase kinase 1 (MAP4K1) gene transcription, with the consequent inhibition of c-Jun activation and Activator Protein-1 (AP-1)-dependent transcription." (PMID 23724959, 2013). "In colon tumor cells, PDCD4 regulates the expression of the JNK upstream kinase MAP4K1 by c-Myc, resulting in the activation of JNK and c-Jun, to control the activation of AP-1." (PMID 31620370, 2019). "A mutation in the c-Myc binding site of the MAP4K1 promoter could reduce MAP4K1 promoter activity, and the downregulation of c-Myc can restore MAP4K1 expression and the activation of AP1 in PDCD4-knockdown colon tumor GEO and HT29 cells." (PMID 31620370, 2019). "Investigations haverevealed that PDCD4 could inhibit c-Jun activation, as well as activating transcriptionfactor-1 (AP-1)-dependent transcription through the downstream MAP4K1/JNK/AP-1 signalingpathway, in colon carcinoma cells." (PMID 27240294, 2016).
lung carcinoma (7 papers, 2014 to 2025). "PDIA6 induces apoptosis of lung cancer cells by regulating the MAP4K1/JNK signaling pathway." (PMID 34616670, 2021).
autoimmune disease (6 papers, 2019 to 2023). A disorder resulting from loss of function or tissue destruction of an organ or multiple organs, arising from humoral or cellular immune responses of the individual to their own tissue constituents. "Our study documents a novel TBK1 inhibitor, which serves as a potential therapeutic target for autoimmune diseases, and elucidated a significant function for MAP4K1 linked to innate immunity in addition to subsequent adaptive immunity." (PMID 34908452, 2021). "Therefore, this study documents a novel TBK1 inhibitor, which serves as a potential therapeutic target for autoimmune diseases, and elucidated a significant function for MAP4K1 linked to innate immunity and subsequent adaptive immunity." (PMID 34908452, 2021). "Moreover, MAP kinase kinase kinase kinases 1 (MAP4K1) regulates the phosphorylation or ubiquitination of downstream target proteins through B cell receptor signal to regulate the immune response and influence the occurrence and development of autoimmune diseases (Chuang, Wang & Tan, 2016)." (PMID 37525657, 2023). "Moreover, MAP4K1 downregulation and MAP4K3 overexpression in T cells are involved in human autoimmune diseases such as psoriatic arthritis, rheumatoid arthritis (RA), adult-onset Still’s disease, and SLE." (PMID 31766293, 2019).
gastric cancer (5 papers, 2019 to 2025). A primary or metastatic malignant neoplasm involving the stomach. "The MAP4K1 protein inhibits apoptosis and metastasis in gastric cancer, and this has been linked to its upregulation of the interaction of lncRNA DLX6-AS1 with miRNA expression." (PMID 37245177, 2023). "The MAP4K1 protein upregulates the interaction of lncRNA DLX6-AS1 with miR-204-5p expression in gastric cancer (GC), promoting invasion." (PMID 37245177, 2023). "Recently, DLX6-AS1 was found to modulate gastric cancer progression via FUS-regulated MAP4K1." (PMID 31787849, 2019). "In gastric cancer, DLX6-AS1 modulates FUS expression, which in turn enhances MAP4K1 mRNA stability through interaction with the FUS protein." (PMID 41034525, 2025). "FUS could also bind to lncRNA DLX6-AS1 to regulate MAP4K1, thus promoting cell proliferation, migration and EMT of gastric cancer." (PMID 34404765, 2021).
breast carcinoma (3 papers, 2019 to 2024). "Studies have shown that progesterone promotes MAP4K1 expression in estrogen-driven breast cancer." (PMID 39247918, 2024).
cutaneous melanoma (2 papers, 2020 to 2024). A primary melanoma arising from atypical melanocytes in the skin. "Of note, the survival effect of MAP4K1 expression in relation to TGF‐β signaling became more significant in metastatic cutaneous melanoma compared to primary cutaneous melanoma." (PMID 38828677, 2024). "However, we did identify a MAP4K1 (MEKKK1; HPK) mutation (P422Q), which was previously identified in a patient with cutaneous melanoma (cBioportal website)." (PMID 33122628, 2020).
glioblastoma (2 papers, 2023 to 2025). The most malignant astrocytic tumor (WHO grade IV). "MAP4K1 acts as a cancer cell-intrinsic driver of tumorigenesis and immune evasion in human gliomas, specifically glioblastoma multiforme, by modulating cytokine–chemokine signaling networks." (PMID 37734869, 2023). "Whether and how cancer cell-intrinsic MAP4K1 contributes to glioblastoma multiforme (GBM) progression remains unclear." (PMID 37734869, 2023).
melanoma (2 papers, 2020 to 2024). A malignant, usually aggressive tumor composed of atypical, neoplastic melanocytes. "The TGF‐β signaling pathway was significantly enriched in NK cells expressing MAP4K1 compared to that in NK cells with undetectable MAP4K1 expression using scRNA‐seq data from malignant melanoma tissues." (PMID 38828677, 2024). "Moreover, NK cells with MAP4K1 expression exhibited significantly increased exhaustion signature (PDCD1, TIGIT, HAVCR2, and LAG3) in melanoma tissues (GSE120575 and GSE72056)." (PMID 38828677, 2024). "Malignant melanoma that did not respond to immunotherapy had more NK cells expressing MAP4K1." (PMID 38828677, 2024).
pancreatic ductal adenocarcinoma (2 papers, 2020 to 2023). An infiltrating adenocarcinoma that arises from the epithelial cells of the pancreas. "In human pancreatic cancer, MAP4K1 loss is associated with the development of invasive pancreatic ductal adenocarcinomas, and its restoration in pancreatic ductal adenocarcinoma cells inhibits cell proliferation and reduces invasion potential by inducing degradation of oncogenic kinase AXL." (PMID 37734869, 2023).
amyotrophic lateral sclerosis (1 paper, 2012). Amyotrophic lateral sclerosis (ALS) is a neurodegenerative disease characterized by progressive muscular paralysis reflecting degeneration of motor neurons in the primary motor cortex, corticospinal tracts, brainstem and spinal cord. "Copz1 and map4k1 are also dysregulated in amyotrophic lateral sclerosis patients." (PMID 22952715, 2012).
bladder cancer (1 paper, 2013). "In endometrial carcinoma, the effect on cell cycle has been confirmed and its impairment of apoptosis has been described and miR-96 controls invasion and differentiation in bladder cancer cell lines via regulation of IRS1 and MAP4K1." (PMID 24260486, 2013).
cervical cancer (1 paper, 2023). A primary or metastatic malignant neoplasm involving the cervix. "Additionally, the method allowed for patient survival analysis, with the Cox regression model selecting gene MAP4K1 in cervical cancer and Kaplan-Meier confirming that upregulation is favourable." (PMID 37093793, 2023).
glioma (1 paper, 2023). A benign or malignant brain and spinal cord tumor that arises from glial cells (astrocytes, oligodendrocytes, ependymal cells). "MAP4K1 was differentially expressed in gliomas according to IDH status, WT or mutation (mut)." (PMID 37734869, 2023). "Furthermore, we found that the elevated expression of MAP4K1 was associated with the clinicopathological characteristics of glioma patients." (PMID 37734869, 2023). "To investigate the molecular mechanisms by which MAP4K1 promotes tumorigenesis in gliomas, we assessed transcriptomic changes after MAP4K1 down-regulation in T98G cells using next-generation RNA sequencing (RNA-seq)." (PMID 37734869, 2023). "Here, our findings suggest that MAP4K1 is expressed in the cytoplasm of human glioma cells and that its levels are positively correlated with the histopathological grading of gliomas." (PMID 37734869, 2023). "TCGA data analysis showed that MAP4K1 mRNA was overexpressed in both low-grade gliomas (n = 523) and GBM (n = 166) compared with that in normal cerebral cortex samples (n = 207)." (PMID 37734869, 2023). "Correlatedly, in subcutaneous mouse GL261 gliomas, the MAP4K1-KD group exhibited increased intratumoral infiltration of CD8+ T cells, rather than CD4+ T cells, compared with that of the NC groups." (PMID 37734869, 2023). "Our data provide a novel mechanism by which the down-regulated MAP4K1 signaling pathway is responsible for the improved survival of patients with IDH mut gliomas." (PMID 37734869, 2023). "We evaluated the clinical relevance of MAP4K1 levels with prognosis and pathological features in patients with gliomas." (PMID 37734869, 2023). "Immunofluorescence analysis showed an obviously increased accumulation of CD8+ T cells in intracranial MAP4K1-KD-GL261 gliomas." (PMID 37734869, 2023). "MAP4K1 mRNA presented higher levels in IDH wt gliomas than in the IDH mut subset and was especially prevalent in IDH wt GBM." (PMID 37734869, 2023). "IHC staining showed that both IL-18R and IL-6R protein levels were down-regulated by MAP4K1-KD in mouse subcutaneous glioma tissues constructed with U87 cells compared with those in NC groups." (PMID 37734869, 2023). "Next, the analysis of mRNA sequencing data from the Cancer RNA-Seq Nexus database (GSE59612) showed elevated MAP4K1 mRNA levels in human gliomas compared with those in normal brain tissues, which was consistent with the IHC results." (PMID 37734869, 2023). "Correlation analysis from different CGGA datasets (batch 2 and batch 1) showed a positive correlation of MAP4K1 with either IL-18R or IL-6R mRNA levels in human gliomas." (PMID 37734869, 2023). "IHC staining with proliferation marker Ki-67 showed that fewer cells were Ki-67-positive in MAP4K1-KD tumors relative to NC tumors, indicating that MAP4K1 promotes glioma cell proliferation in vivo." (PMID 37734869, 2023). "In this study, we show that MAP4K1 is intrinsically expressed by cancer cells in human high-grade glioma (HGG) tissues." (PMID 37734869, 2023). "Immunohistochemistry (IHC) analysis of tissue microarray slides showed that MAP4K1 proteins exhibited higher expression levels in glioma tissues than in para-tumor tissues and were mainly localized in the cytoplasm of glioma cells." (PMID 37734869, 2023). "Most of the inhibitors of MAP4K1 that are in development are in the preclinical research and discovery stage, which may bring new therapeutic prospects for gliomas." (PMID 37734869, 2023). "We found that MAP4K1 was highly expressed in the glioma cells of human GBM specimens." (PMID 37734869, 2023). "We found that patients with comparatively higher levels of MAP4K1 mRNA had a lower rate of overall survival than patients with low levels of MAP4K1 mRNA, suggesting that MAP4K1 up-regulation signifies a poorer prognosis for patients with gliomas." (PMID 37734869, 2023). "Furthermore, MAP4K1 KD in GL261 cells limited tumor growth in mouse intracranial glioma models." (PMID 37734869, 2023).
glioma (continued). "First, we explored whether MAP4K1 proteins are expressed by cancer cells in human glioma samples." (PMID 37734869, 2023). "MLK3, the downstream kinase of the MAP4K1 pathway, predicts poor prognosis in patients with IDH-wt gliomas and regulates cytoskeleton remodeling of GBM cells by directly binding EPS8." (PMID 37734869, 2023). "MAP4K1-overexpressing glioma cells were primarily present in HGG (grades III–IV), especially in GBM (Grade IV), indicating a positive correlation of MAP4K1 levels with glioma progression." (PMID 37734869, 2023). "In addition, GBM cell-derived MAP4K1 impaired T-cell migration and reduced CD8+ T-cell infiltration in mouse glioma models." (PMID 37734869, 2023). "MAP4K1 silencing inhibited GBM cell proliferation and glioma growth." (PMID 37734869, 2023). "We noticed that the levels of CCL8 mRNA were positively correlated with those of MAP4K1 in human gliomas and predicted poor clinical outcomes of patients (data not shown)." (PMID 37734869, 2023). "The levels of MAP4K1 were positively correlated with glioma WHO grade but not gender, age or tumor size." (PMID 37734869, 2023). "We found that high levels of MAP4K1 are associated with a malignant phenotype and subclasses (IDH-wt, 1p/19q noncodeletion) of human gliomas, signifying poor prognosis of patients." (PMID 37734869, 2023). "Similarly, MAP4K1 mRNA was predominantly prevalent in the 1p/19q non-codeletion glioma cohort." (PMID 37734869, 2023). "High levels of MAP4K1 mRNA were prevalent in IDH-WT and 1p/19q non-codeletion gliomas and correlated with poor prognosis of patients." (PMID 37734869, 2023). "Therefore, MAP4K1-targeted therapy is suitable for IDH-wt and 1p/19q non-codeletion gliomas." (PMID 37734869, 2023).
malignant glioma (1 paper, 2023). A grade III or grade IV glioma arising from the central nervous system. "The present data contribute to a better understanding of the pathological relevance of MAP4K1 and the underlying mechanisms in GBM progression, indicating that MAP4K1 is a potential molecular therapeutic target for malignant gliomas." (PMID 37734869, 2023). "Targeting the MAP4K1 pathway is a promising strategy for not only molecular-targeted therapy but also immunotherapy, which allows us to kill two birds with one stone for treating malignant gliomas." (PMID 37734869, 2023). "Based on the transcriptome profiles of human GBM, we hypothesized that GBM cell-derived MAP4K1 modulates the expression and secretion of various cytokines and chemokines to retrain the immune responses in the microenvironment of malignant gliomas." (PMID 37734869, 2023). "Therefore, MAP4K1 is a reliable drug target for the treatment of malignant gliomas." (PMID 37734869, 2023). "On the other hand, GBM cell-intrinsic MAP4K1 inhibits CD8+ TIL invasion and migration to promote immune evasion in malignant gliomas." (PMID 37734869, 2023).
non-small cell lung carcinoma (1 paper, 2022). A group of at least three distinct histological types of lung cancer, including non-small cell squamous cell carcinoma, adenocarcinoma, and large cell carcinoma. "The combination of CALR and PDIA3 has also been suggested as a possible prognostic biomarker for non-small-cell lung cancer, with PDIA6 modulating apoptosis and autophagy of non-small-cell lung cancer cells via the MAP4K1/JNK signalling pathway." (PMID 36291587, 2022).